IL10 (interleukin 10)
Diseases named in the same sentence as IL10 in open-access papers (continued):
Sharing a sentence is not in itself a finding about the gene and the disease.
tongue squamous cell carcinoma (6 papers, 2017 to 2022). A squamous cell carcinoma that arises from the tongue. "A very recent study highlighted that, in tongue squamous cell carcinoma, the immune response was biased toward Th2, with their cytokines (IL-4, IL-10) suppressing the cytotoxicity of CTL." (PMID 35047982, 2020). "Moreover, IL-10 facilitates cross talk between CD19+IL-10+ Bregs and CD4+CD25− T cells in tongue squamous cell carcinoma patients, resulting in the conversion of these resting T cells into Tregs." (PMID 28261223, 2017).
Zinc deficiency (6 papers, 2010 to 2023). A deficiency of the essential metal Zinc; an essential cofactor for many enzymes. "Zinc deficiency leads to dysregulation of IL-10 production (an anti-inflammatory cytokine) that affects the Th1 response and macrophages functions." (PMID 35599332, 2022). "Zinc deficiency has impacts on IL-10 production that affects the Th1 response and macrophages functions." (PMID 35599332, 2022). "Zinc deficiency leads to a dysregulation of interleukin-10 (IL)-10, IL-2, and IFN-γ production." (PMID 36678229, 2023). "With slightly decreased levels of IL-10 in association with malaria infection in zinc deficient children, the findings possibly reflect that zinc deficiency primarily results in pathological consequences of type I cytokines due the reduced regulatory role of the cytokine IL-10." (PMID 20546583, 2010). "Similar to our results, studies in both murine and human primary monocytes had shown zinc deficiency to impair TLR4-mediated signaling that resulted in reduced production of cytokines such as TNF-α, IL-6, IL-10, and Il-1β." (PMID 36558553, 2022). "In the absence of malaria infection at the time of blood collection, zinc deficiency was associated with marginal reductions in concentrations of TNF, IL-1β and IL-10." (PMID 20470442, 2010). "In children with malarial infection, zinc deficiency was associated with increased production of IL-1β and IL-10, even if this increase did not bring the levels to those reached by individuals in the non-infected group." (PMID 20470442, 2010). "For instance, zinc deficiency reduced production of Th1 cytokines, in particular IFN-γ, IL-2, and tumor necrosis factor (TNF)-α, whereas levels of Th2 cytokines IL-4, IL-6, and IL-10 were not affected." (PMID 29196724, 2017).
allergic bronchopulmonary aspergillosis (5 papers, 2012 to 2024). Allergic bronchopulmonary aspergillosis (ABPA) is a rare immunologic pulmonary disorder caused by hypersensitivity to Aspergillus fumigatus, clinically manifesting with poorly controlled asthma and recurrent pulmonary infiltrates. "However, IL-10 seems to be protective in regulating exaggerated immune responses and inflammation in allergic bronchopulmonary aspergillosis, suggesting that the regulatory role of IL-10 depends on the disease context." (PMID 36177012, 2022). "The allelic variant 1082G/A (rs1800896) causes an increased level of IL10 detected in patients who had airway colonization with A. fumigatus (allergic bronchopulmonary aspergillosis-ABPA), compared to those without infection." (PMID 34945117, 2021). "Similarly, increased levels of serum IL-10 due to single nucleotide polymorphism in the IL10 gene is associated with an increased susceptibility to A. fumigatus colonization and allergic bronchopulmonary aspergillosis." (PMID 29093719, 2017). "For example, allergic bronchopulmonary aspergillosis (ABPA) is characterized by Th2 and Th9 cell-type immunity and involves interleukin (IL)-4, IL-5, IL-13, and IL-10." (PMID 38667922, 2024).
amebiasis (5 papers, 2016 to 2026). A parasitic infectious disorder caused by amoebas. "Very few studies have associated IL-10 levels with amebiasis." (PMID 36678367, 2022). "This study revealed that elevated levels of IL-10 might be associated with a reduced risk of amebiasis." (PMID 36678367, 2022). "The current study also showed that patients with high levels of IL-10 are likely to have a low burden of amebiasis compared to patients who produce low levels of IL-10." (PMID 36678367, 2022). "The present study also confirms a previous study by Hamano and colleagues who showed that IL10 protected C57BL/6 mice from amebiasis." (PMID 36678367, 2022). "TNF-α was a critical cytokine mediator of tissue destruction during amebiasis and the anti-inflammatory cytokine IL-10 is an important immunoregulator." (PMID 26824828, 2016). "Multiple pathways were potentially regulated by several hub genes; for example, ICOS, HLA − A, and CD40LG were related to regulate allograft rejection and cell adhesion molecules; IL10 was related to regulate allograft rejection, amoebiasis, and hematopoietic cell lineage." (PMID 34603484, 2021). "Therefore, elevated levels of IL-10 in the serum may play a significant role in the development of amebiasis." (PMID 36678367, 2022). "However, the impact of IL-10 production on amebiasis–HIV coinfection is not known." (PMID 36678367, 2022).
apical periodontitis (5 papers, 2021 to 2025). "Immunohistochemical staining demonstrated a higher expression of IL-1β and IL-10 in apical periodontitis." (PMID 38612664, 2024). "Notably in the cases of apical periodontitis and pulp necrosis,biomarkers like Interleukin-6 (IL-6) and Interleukin-10 (IL-10) might be employed in endodontics to direct endodontic therapy andevaluate inflammation that occurs in pulpal infections." (PMID 40230914, 2024).
arthropathy (5 papers, 2017 to 2025). Any disorder of the joints. "Additionally, the production of IL‐1β decreased, while IL‐10 levels increased in joint effusion." (PMID 41255239, 2025).
B cell deficiency (5 papers, 2016 to 2025). A broad classification of disorders where circulating numbers of B lymphocytes are decreased or ineffective. "We and others have reported that mice with B cell-deficiency exhibit increased production of IL-10 in the lungs during the acute phase of infection." (PMID 36888692, 2023). "This B cell deficiency-associated IL-10 phenotype is also apparent at 24 weeks post-infection, with the PPD-stimulated lung cells of μMT strain producing 150% of the cytokine generated by that of the C57BL/6 mice (p<0.005)." (PMID 36888692, 2023). "Studies of other mouse models have demonstrated that B cell deficiency delays the appearance of Treg cells and IL-10 in the central nervous system during EAE." (PMID 26785945, 2016).
bacterial vaginosis (5 papers, 2011 to 2024). Infection caused by bacterial overgrowth in the vagina. "Association of bacterial vaginosis, IL-10 and TGF-β with preterm birth adjusted for confounding variables." (PMID 27486805, 2016). "Indeed, bacterial vaginosis has been associated with increased levels of IL-1 beta, IL-6, IL-8, IL-10 and TNF-alpha, RANTES (CCL5), macrophage inflammatory protein (MIP-1 alpha/CCL3) and MIP-1 beta (CCL4) in genital samples." (PMID 21966450, 2011). "In our study, we found elevated IL-10 levels in a group of mice with bacterial vaginosis, which is consistent with previous studies." (PMID 39598357, 2024). "The reduction of an anti-inflammatory cytokine IL-10 concentration by CSA-13 and CSA-131 in comparison to the control group with bacterial vaginosis necessitates additional clarification." (PMID 39598357, 2024). "In contrast, TNF-α, IL-10, and RANTES were down-regulated in bacterial vaginosis in patients where L. crispatus dominated." (PMID 33495564, 2021). "Independent of the presence of a bacterial vaginosis, decreased IL-10 levels at mid-pregnancy were suggested to be useful as an early predictor of PTB." (PMID 32265904, 2020).
cervical disease (5 papers, 2014 to 2017). "Additionally, we demonstrated a potential association of a HLA class I haplotype (HLA-B*14-C*08) with higher IL-10 cytokine serum levels in cervical disease, suggesting an association between HLA class I and specific cytokines in cervical carcinogenesis." (PMID 28858203, 2017). "Additionally, we demonstrated a potential association of HLA class I polymorphism with higher IL-10 cytokine levels in cervical disease." (PMID 28858203, 2017). "The protein expression levels of Foxp3 and IL-10 increased along with the progression of pathology of cervical disease." (PMID 24837834, 2014). "Additionally, other cytokines related to immune response modulation, such as IL-17 and IL-10, appears to play a paradoxical role in cervical disease, although mixed results have been reported." (PMID 28858203, 2017). "Furthermore, the protection from cervical disease progression may be due to the anti-inflammatory and anti-angiogenic effects of IL-10." (PMID 28858203, 2017). "After accounting for high-risk-HPV, age, and use of oral contraceptive, they found IL-10 was an independent covariate of CIN2/3, suggesting that this immunosuppressive cytokine might play an important role in creating a milieu that favors progressive cervical disease." (PMID 25810759, 2015).
cervical tumor (5 papers, 2010 to 2025). "As regulatory T cells play a role in human cervical tumors and as we had previous indication that tumor associated macrophages induced regulatory phenotype on T cells, we investigated if IL-10 may have a role in expansion of regulatory T cells in our model." (PMID 20525400, 2010). "On the one hand, the presence of large amounts of IL-10 in the cervical tumor microenvironment was confirmed; on the other hand, there was a negative correlation between the level of IL-10 and the expression of class I human leukocyte antigens (HLAs)." (PMID 35752792, 2022). "Type-2 cytokine, IL-10 shows immunosuppressive functions and is capable of stimulating tumor growth, and cervical tumor biopsies showed increased presence for mRNA for IL-10." (PMID 33946372, 2021).
Chagas cardiomyopathy (5 papers, 2012 to 2025). A disease of the cardiac muscle developed subsequent to the initial protozoan infection by trypanosoma cruzi. "They observed that Chagas cardiomyopathy was associated with higher median values of IL-10 and lower levels of IFN-γ compared to indeterminate Chagas." (PMID 38133693, 2023). "On the other hand, our data confirmed the involvement of IL12B and IL10 in the control of susceptibility to human Chagas cardiomyopathy." (PMID 32733459, 2020). "It found an association between interleukin-10 (IL-10) 1082G/A polymorphism and susceptibility to Chagas cardiomyopathy." (PMID 22790551, 2012). "Furthermore, TLR-2 and TLR-4 expression are associated with the production of pro-inflammatory cytokines in Chagas’ cardiomyopathy, while in asymptomatic patients these receptors as predominantly associated with IL-10 and TGF-β production." (PMID 29599775, 2018). "Research suggests that individuals at high risk of sudden death in Chagas cardiomyopathy exhibit elevated serum levels of IFN-γ, TNF-α, IL-6, IL-2, IL-10, and IL-4 compared to those at low risk." (PMID 39907396, 2025). "The individuals with an indeterminate state had higher IL-10 expression, whereas the Chagas cardiomyopathy group presented the highest inflammatory cytokine expression (IFN-γ, TNF-α, IL-6 and IL-1β)." (PMID 38133693, 2023).
coccidioidomycosis (5 papers, 2017 to 2023). A fungal infection caused by Coccidioides immitis. "Furthermore, production of the anti-inflammatory cytokine, IL-10, is also associated with the susceptibility of mice to pulmonary Coccidioides infection." (PMID 28300772, 2017). "Mice more resistant to Coccidioides infection (DBA/2) have lower number of Tregs and IL-10 production compared to susceptible mice (C57BL/6 and BALB/C), suggesting that Tregs may be detrimental in coccidioidomycosis." (PMID 34065016, 2021). "Dogs with coccidioidomycosis produced higher coccidioidal stimulated supernatant concentrations of TNF-α (p = 0.003), IL-6 (p = 0.04), IFN-γ (p = 0.03), MCP-1 (p = 0.02), IL-10 (p = 0.02), and lower IL-8 (p = 0.003) than controls." (PMID 36836327, 2023). "DCs from C57BL/6 mice produce more IL-10 than DCs from DBA/2 mice, resulting in the detrimental outcome of coccidioidomycosis in C57BL/6 mice." (PMID 28300772, 2017). "Likewise, dogs with coccidioidomycosis produced higher concentrations of TNF-α (p < 0.0001), IL-6 (p < 0.0001), GM-CSF (p = 0.03), IL-8 (p = 0.02), IFN-γ (p = 0.03), KC-like (p = 0.01), MCP-1 (p = 0.01), and IL-10 (p = 0.0004) with coccidioidal stimulation compared with unstimulated control." (PMID 36836327, 2023).
colonic disease (5 papers, 2009 to 2023). "Second, it is entirely possible that the colonic disease in this animal model is not only generated by events that occur proximally in the small intestine, but also by direct interaction of the colonic bacterial flora with the IL10 deficient immune system." (PMID 18829978, 2009). "Mice with conditional ablation of IL-10 in Foxp3+ Tregs (IL-10cKO) are largely spared from the severe colonic disease that global IL-10KO mice develop (Ref." (PMID 37314833, 2023). "This suggests that the early evidence of colonic disease, observed in IL10−/− mice, is prevented or delayed by treatment with AT-1001." (PMID 18829978, 2009). "We investigated whether IL10/Nox1dKO mice had longstanding colonic disease complications by analyzing the late colonic evolution in 8-month old IL10/Nox1dKO mice (n = 35)." (PMID 25014110, 2014). "Even though gnotobiotic IL-10-/- mice are considered a suitable model for severe C. jejuni induced colonic disease, we addressed whether peroral infection with the respective bacterial strains might also affect pro-inflammatory cytokine secretion in the small intestinal tract." (PMID 27438014, 2016).
Constipation (5 papers, 2017 to 2025). Infrequent or difficult evacuation of feces. "We found the reduced levels of TGF-β, IL-10, and IL-21, and the increased levels of GM-CSF, IL-17A, IL-17F, IL-22, and IL-23 in the serum of constipation EAE mice." (PMID 34301274, 2021). "We found that the concentrations of TGF-β, IL-10, and IL-21 were decreased while the levels of GM-CSF, IL-17A, IL-17F, IL-22, and IL-23 were increased in constipation EAE mice and FMT EAE mice compared to EAE mice." (PMID 34301274, 2021). "An important factor in the pathogenesis of constipation is the dysfunction of intestinal immunoregulation, and pro-inflammatory factors (IL-1β, IL-6, IL-8, IFN-γ, TNF-α) and anti-inflammatory factor IL-10 are key indicators of the degree of inflammation in the constipation model." (PMID 40718808, 2025). "Moreover, the serum levels of TGF-β, IL-10, and IL-21 were decreased while the GM-CSF, IL-17A, IL-17F, IL-22, and IL-23 were increased in the constipation EAE mice." (PMID 34301274, 2021). "However, the level of serum IL-10 and IL-12 were decreased in the constipation-induced group compared to the control group and were recovered with the administration of HLp-nF1 or Dulcolax (Dul)." (PMID 33872333, 2021). "In summary, this study revealed that EXQ effectively alleviated constipation by improving fecal output, alleviating the concomitant inflammatory responses by enhancing sIgA level, and reducing the levels of IL-10, TNF-α and LPS in constipated mice induced by HHPD and HHPD + atropine." (PMID 28359333, 2017).
corneal disease (5 papers, 2012 to 2026). "In a completely different set of studies to determine the role of IL-10 during HSK, it was reported that intraocular treatment of mice with IL-10 reduced corneal disease from 95% to 36%." (PMID 22593769, 2012). "Furthermore, treating mice with recombinant IL-10 led to significantly reduced corneal disease." (PMID 22593769, 2012). "Our laboratory also evaluated the role that IL-10 plays during recurrent HSK, and similar to what was reported during primary HSK, lack of IL-10, as determined by neutralizing IL-10 or using IL-10 KO mice, resulted in very severe corneal disease." (PMID 22593769, 2012). "In line with our findings, a previous study demonstrated that eyes undergoing DMEK showed elevated levels of the proinflammatory mediators interferon-γ, interleukin-8, and interleukin-10 compared with eyes without corneal disease scheduled for cataract surgery." (PMID 41244993, 2026). "In this study, we evaluated the cytokine profiles of IL-2, IFN-γ, ICAM-1, IL-5, IL-6, IL-8, IL-10, IL-1β, MCP-1, IL-17A, IP-10, G-CSF, and VEGF-A in the AqH of BK patients before and after DMEK and in a control group without corneal disease." (PMID 34426617, 2021).
dental caries (5 papers, 2014 to 2025). The decay of a tooth, in which it becomes softened, discolored, and/or porous. "Among them, only IL-10 and IL-17A showed a significantly higher level in the group of children with dentofacial tissue inflammation compared to the group with uncomplicated dental caries." (PMID 39201367, 2024).
diabetic foot ulcers (5 papers, 2022 to 2024). "This study evaluated the association between Apo A1 and other inflammatory biomarkers like TNF-α and IL-10 and diabetic foot ulcers." (PMID 35836916, 2022). "Increasing age, smoking, retinopathy, eGFR and inflammatory biomarkers like low levels of ApoA1 (p < 0.005) and IL-10 (p < 0.001) significantly contributed to the development of diabetic foot ulcers." (PMID 35836916, 2022). "This study aims to find the association between ApoA1, IL-10, TNF-α, and diabetic foot ulcers and whether their levels can assess the severity of the disease." (PMID 35836916, 2022). "Increased serum levels of IL-10, IL-6, IFN-γ, IL-4 and adiponectin have been shown in patients with diabetic foot ulcers treated with hyperbaric oxygen." (PMID 36198698, 2022).
diffuse cutaneous Leishmaniasis (5 papers, 2006 to 2017). A form of LEISHMANIASIS, CUTANEOUS caused by Leishmania aethiopica in Ethiopia and Kenya, L. pifanoi in Venezuela, L. braziliensis in South America, and L. mexicana in Central America. "In patients with diffuse cutaneous leishmaniasis (DCL) caused by L. (L.)amazonensis there is a predominance of IL-10 and Th2 cytokines." (PMID 24884781, 2014). "In humans, low IFN-γ production has been associated with parasite dissemination, as exemplified by VL and diffuse cutaneous leishmaniasis, in which IL-10 acts to down regulate IFN-γ." (PMID 16638143, 2006). "The current work also extends this mouse analysis to humans, finding that L. mexicana-infected humans with localized and diffuse cutaneous leishmaniasis have antibodies that recognize GIPLs, can bind to the surface of amastigotes, and can induce IL-10 from human monocytes." (PMID 23675550, 2013). "Patients with localized cutaneous lesion (LCL) exhibit predominant expression of iNOS, IL-1β, IL-6, MCP-1, TNF-α, and IFN-γ, while anergic diffuse cutaneous leishmaniasis (ADCL) lesions are characterized by the presence of IL-4, IL-5, IL-10, and MIP-1α and the low expression of iNOS." (PMID 28959260, 2017). "In contrast to what has been observed in VL and diffuse cutaneous leishmaniasis, we found neither a type 2 immune response nor an increase in IL-10 levels in DL patients." (PMID 16638143, 2006).
disc degeneration (5 papers, 2016 to 2025). "In our study, we obtained a significant increase in the protein expression of IL-6 an anti-inflammatory cytokine, while there was a significant decrease of IL-10 that is a pro-inflammatory cytokine at the same time (15 days) of disc degeneration." (PMID 26997908, 2016). "Studies have shown that IL-10 reduction can accelerate disc degeneration in animal models." (PMID 35937989, 2022). "IL-10 acts as an anti-inflammatory cytokine that can limit production of reactive oxygen species and promote metabolic reprogramming; thus, IL-10 may limit disc degeneration through effects on endogenous macrophages." (PMID 38274272, 2023).